INS (insulin)
Diseases named in the same sentence as INS in open-access papers (continued):
Sharing a sentence is not in itself a finding about the gene and the disease.
depression (continued). "This review explores the bidirectional association between depression and AD, focusing on common pathophysiological mechanisms involving glucose metabolism, such as hypothalamic-pituitary-adrenal (HPA) axis dysregulation, insulin resistance, glucose transporters, and oxidative stress." (PMID 39318215, 2025). "Some research suggests that anxiety and depression may cause the development of GDM through sustained activation of the hypothalamic–pituitary–adrenal (HPA) axis, leading to increased cortisol secretion and insulin resistance." (PMID 40870492, 2025). "Given the benefits of technology use in youth with depression, clinicians who continue to be hesitant to prescribe a pump to due to fears of “suicide by insulin” should consider using tailored screening of suicide risk rather than a broader depression or mood measure." (PMID 40460446, 2025). "Insulin avoidance due to anxiety and depression may be relieved through a KD." (PMID 39539363, 2024). "The active natural inositol D-pinitol reduces pancreas insulin secretion and increases circulating ghrelin levels in rats; herein, the increase in D-pinitol in the long-term depression group may provide insight into the mechanism of depression-related weight gain." (PMID 37051300, 2023). "The loss of insulin sensitivity of hippocampal CA1 pyramidal neurons can subsequently cause long-term Ca 2+-dependent afterhyperpolarizations (AHPs), which can produce significant cognitive and memory impairment in the short term and throughout life, contributing to depression." (PMID 37152963, 2023). "One of the most striking findings of this study was that women with GDM requiring insulin had higher rates of mental illness preceding pregnancy than the other groups: 60% of insulin-treated women were taking prescribed medication for anxiety/depression prior to or during pregnancy." (PMID 36733299, 2023). "Therefore, those on insulin treatment may need more regular check-ups for depression in clinical practice." (PMID 36918821, 2023). "Therefore, we hypothesized that several hormonal abnormalities in GD could increase the risk of depression, and we analyzed the specific mechanism regarding hormonal abnormality of the HPT axis, insulin metabolism, and sex hormones." (PMID 37152963, 2023). "Dysregulated insulin signaling in the hypothalamus results in impaired metabolic control of liver and adipose tissue, while disrupted glucose transporters in the hippocampus lead to reduced neuronal plasticity, impaired cognition, and the development of depression." (PMID 36232867, 2022). "Regulates insulin secretion and testosterone production; promotes muscle adaptation to exercise; increases the release of serotonin, dopamine, and norepinephrine; and inhibits the release of γ-aminobutyric acid, thereby reducing depression and anxiety-like behaviors." (PMID 35645958, 2022). "Therefore, we speculate that JTW may play a role in the treatment of DM and depression through the key targets such as INS, AKT1, IL-6, VEGF-A, TNF and so on." (PMID 34875999, 2021). "Because it affects both insulin and depression, this may be a target for future research." (PMID 34366917, 2021). "However, the association between insulin and depression has not been systematically studied through bibliometric and visual analysis." (PMID 34366917, 2021). "Based on the common mechanism of the effect of insulin on depression and the effect of exercise on depression, it can be speculated that the positive effect of exercise on metabolic homeostasis may be due to the recovery of insulin levels in the body." (PMID 34366917, 2021). "Due to its ability to increase insulin sensitivity, ALA could help improve the influx of tryptophan into the brain, causing an increase in serotonin synthesis and resulting in a reduction in depression." (PMID 33614362, 2021). "Therefore, this review may provide new insight for clarifying the role of insulin on the pathogenesis of depression." (PMID 32281722, 2020).
depression (continued). "Therefore, in this review, we summarized the potential role of insulin on depression." (PMID 32281722, 2020). "Therefore, insulin dysregulation has been hypothesized to play a role in neuropsychiatric conditions such as dementia and depression." (PMID 32545890, 2020). "However, the role of insulin on depression remains largely unclear." (PMID 32281722, 2020). "In addition, a small number of studies have been reported for a role of insulin in depression." (PMID 33256267, 2020). "Moreover, impaired insulin signaling may contribute to the pathogenesis of depression by regulating dopaminergic neurotransmission." (PMID 32971941, 2020). "Understanding the interaction of the gastrointestinal microbiome with insulin provides some treatments that may be superior to standard antidepressants and shows the potential of regulating the gastrointestinal microbiome to treat depression." (PMID 32281722, 2020). "Therefore, it is suggested that improvement of insulin resistance in the brain does not decrease the risk of depression." (PMID 31768258, 2019). "Therefore, diabetic patients on insulin or OAD are more prone to getting depression and stress." (PMID 31638930, 2019). "In addition, when a “next generation antidepressant” L-acetylcartinine (LAC) is administered to a genetic rat model of depression (Flinders Sensitive Line), the treatment reduces insulin and glucose levels, suggesting an insulin resistant state that responds to LAC." (PMID 29085297, 2017). "Therefore, we aimed to include a sample of people with less severe diabetes (i.e. not using insulin) and also report on the associations with both anxiety and depression." (PMID 27537359, 2016). "We believe that light therapy may be a promising treatment option for patients with major depression and T2D, as light therapy may result in concurrent improvements in depressive symptoms and insulin sensitivity through restoration of the circadian rhythmicity." (PMID 26204994, 2015). "Stepwise logistic regression showed that depression was an independent factor for failure to attain HbA1c target to <7.0%, in addition to young age, long disease duration, low education level, smoking, higher body mass index, and use of insulin (Model 1 and 2)." (PMID 25349949, 2015). "Thus, BDNF and cortisol may possibly explain the link between depression and glycated hemoglobin (HbA1c), insulin resistance, LDL and HDL." (PMID 26231223, 2015). "There may be a bidirectional relationship between insulin metabolism and depression." (PMID 31667005, 2013). "Cox regression analyses were used to determine whether there was a difference in time to insulin initiation between people with a low versus a high depression score at baseline, adjusting for potential demographic and clinical confounders, including HbA1c levels." (PMID 24223860, 2013). "In addition, chromium was linked to improved insulin sensitivity and glucose metabolism, which can benefit not only metabolic health but also mood regulation, with specific benefits on atypical symptoms of depression, such as appetite/weight gain." (PMID 40345207, 2025). "This study further explored the potential links between three insulin-related metabolic indices—LAP, TyG, and HOMA-IR—and the prevalence of depression." (PMID 40551244, 2025). "However, the physiological pathways by which physical activity prevents preterm birth may include improving maternal mental health, including mood and reducing depression during pregnancy, increasing insulin sensitivity, reducing inflammatory responses, and reducing oxidative stress." (PMID 39888941, 2025). "Disrupted insulin signaling in T2DM can decrease glycaemic control, and depression can affect insulin signing." (PMID 39540008, 2024). "Depression elevates cortisol and catecholamine levels by modifying the HPA axis, thereby counteracting the hypoglycemic effects of insulin and leading to insulin resistance." (PMID 39596474, 2024).
depression (continued). "The olfactory bulbectomized rat models of depression demonstrated a reduction in overall cerebral glucose utilization, while rats exposed to CUMS exhibited insulin resistance specifically within the arcuate nucleus of the hypothalamus." (PMID 38358062, 2024). "Patients with depression had higher serum triglyceride, HbA1c, ACR and eGFR, and were more likely to be treated with insulin." (PMID 38586459, 2024). "Therefore, the risk of comorbid depression among hospitalized T2DM patients might be reduced through enhancing physical activity and offering more social support in clinical practice, and those on insulin treatment should be paid special attention for preventing comorbid depression." (PMID 36918821, 2023). "A large meta-analysis found increased insulin levels and HOMA-IR in patients with depression, which was consistent with our findings." (PMID 37032915, 2023). "We also performed genetic correlations between our sex-specific broad depression MDD GWAS and previously published sex-specific GWAS for ADHD and for fasting insulin." (PMID 36750733, 2023). "We also tested 9 other potential mediators (testosterone, androstenedione, dehydro-epiandrosterone (DHEA), insulin, HOMA-IR, cortisol, oligomenorrhea and depression." (PMID 35581616, 2022). "Significant genetic correlations with insulin-related phenotypes were also found for anorexia nervosa (AN), attention-deficit/hyperactivity disorder (ADHD), major depressive disorder, and schizophrenia (p < 6.17 × 10−4)." (PMID 35165256, 2022). "Moreover, depression can involve feelings of hopelessness and helplessness, which can influence the individual’s motivation to adopt healthy behaviors, namely following a healthy diet, doing regular physical activity, and taking oral medication and/or insulin injections." (PMID 34501572, 2021). "Age, BMI, WHR, and FAI were associated with both anxiety and depression-like symptoms, while hirsutism was an important factor for anxiety-like behaviors and fasting insulin, FBG, and HOMA-IR were important factors for depression-like behaviors." (PMID 34744814, 2021). "It is worth noting that the factors of age, BMI, W, T, FAI, fasting insulin, and HOMA-IR were significantly correlated with both anxiety-like and depression-like behaviors." (PMID 34744814, 2021). "In our study, fasting insulin, FBG, and HOMA-IR were significantly negatively correlated with SDS-SS in women with PCOS, and metabolic disorder was an important factor affecting depression-like behaviors." (PMID 34744814, 2021). "They discovered beneficial effects using measures of the Beck Depression Inventory (BDI), insulin levels and inflammation markers after eight weeks of probiotic intake." (PMID 32718072, 2020). "Brain insulin signaling is accounted for the development of a variety of neuropsychiatric disorders, such as anxiety and depression, whereas both inflammation and the activated renin-angiotensin system (RAS) are two major contributors to insulin resistance." (PMID 31001119, 2019). "It concluded that exercise was beneficial for BC survivors because it improved the QoL, body configuration, and muscle strength, decreased serum levels of insulin, IGF-II, and IGFBP-1, and alleviated depression and anxiety." (PMID 31759342, 2019). "Participants with high level of fasting insulin (Q2 to Q4) and HOMA-IR (Q2 to Q4) had significantly higher depression score than those with the lowest." (PMID 26891344, 2016). "In the present study, odds of high fasting insulin and high HOMA-IR increased by nearly 30% in the highest group of depression score in participants." (PMID 26891344, 2016). "Further, there was a trend for fasting insulin to be higher (P = 0.07) and HDL-C (P = 0.09) to be lower in BCS with depression." (PMID 27453736, 2016). "Participants in the highest quartile of depression score showed significantly higher SFA, fasting insulin and HOMA-IR levels than those in the lowest quartile of depression score." (PMID 26891344, 2016).
depression (continued). "Additional studies in other samples, preferable incorporating more information about the decision making process that leads to insulin initiation (or not), are needed to further elucidate whether or not depression is associated with initiation of insulin therapy." (PMID 24223860, 2013). "The proportions of patients who reported at least some problems with “anxiety/depression” were 46.9% at baseline and 35.4% at 24 months in the exenatide BID cohort; respective values were 47.6% and 35.9% in the insulin cohort." (PMID 24369764, 2013). "For depression, 66.2% of exenatide BID and 60.6% insulin patients had responses “within the normal range”." (PMID 24369764, 2013). "However, the wide 95% confidence interval around this estimate (2.7–74.9) hints to a relatively small number of individuals with depression in this sample and consequently, this study does not allow any firm inferences about the association between insulin use and depression." (PMID 24223860, 2013). "Therefore, it may be hard to characterize the association between depression and insulin initiation, without knowing more about the driving factors behind these treatment decisions." (PMID 24223860, 2013). "Participants completed the PAID, Centre for Epidemiological Studies Depression Scale (CES-D), Insulin Treatment Appraisal Scale (ITAS), and World Health Organization-Five Well-Being Index (WHO-5) questionnaires." (PMID 22195273, 2011). "One possible explanation is that alcohol and depression exert independent and additive effects on glucose metabolism through distinct physiological pathways—such as hepatic insulin resistance in the case of alcohol and HPA axis dysregulation in the case of depression." (PMID 40870425, 2025). "Insulin-dependent patients exhibit a higher incidence of depression and anxiety than their noninsulin-dependent counterparts." (PMID 40135018, 2025). "Increased anxiety and depression in GDM women may lead to poor glycemic control through neuroendocrine mechanisms, including elevated cortisol and catecholamine levels that impair insulin sensitivity." (PMID 40870492, 2025). "Depression-induced dysregulation of the ANS, characterized by increased sympathetic activity and reduced parasympathetic tone, worsens glycemic control by impairing insulin secretion and promoting hepatic glucose output." (PMID 40218134, 2025). "In the remaining patients without complications, 11.9% had depression who were more likely to be women, had younger age and treated with insulin." (PMID 38586459, 2024). "Among patients without depression, no longer meeting PTSD criteria was associated with a lower risk of insulin initiation (HR, 0.73 [95% CI, 0.55-0.97])." (PMID 39136942, 2024). "Among those without depression, no longer meeting PTSD criteria was associated with a lower risk of insulin initiation (HR, 0.73 [95% CI, 0.55-0.97]; P = .03) (eTable 5 in Supplement 1)." (PMID 39136942, 2024). "There was no clear evidence of causality between genetically predisposed RC and HDL-C, BMI, circulating CRP, fasting blood glucose, fasting blood insulin, hip circumference, waist circumference, WHR, alcohol consumption, smoking status, overweight, HOMA-IR, insomnia, sleep apnoea, or depression." (PMID 37563569, 2023). "The results of the present study revealed that six months of fixed combination of insulin degludec and liraglutide did not affect depression and cognitive function assessed by GDS and MMSE, respectively." (PMID 37008061, 2023). "In particular, vulnerability models propose that suboptimal levels of insulin, fasting glucose, triglycerides, LDL, and HDL might influence future somatic (v. mood and interpersonal) aspects of depression." (PMID 35924730, 2023). "First, since this study analyzed secondary data by analyzing epidemiological data (survey data), clinical indicators such as insulin-antagonizing hormones and genes related to depression were not included." (PMID 37533521, 2023).
depression (continued). "Although depression scores tended to be higher in GDM-Insulin and GDM-Diet groups than in the non-GDM group at both time points, this was not statistically significant." (PMID 36733299, 2023). "For example, short-term effect of citalopram did not affect glucose homeostasis and insulin sensitivity in women with depression." (PMID 37653558, 2023). "No significant BDNF rhythm was found in the plasma, frontal cortex or SCN of SP acclimated animals, which also had higher insulin levels, significantly higher glucose levels in the OGTT, and significantly higher anxiety- and depression-like behaviors compared with animals acclimated to NP." (PMID 36160856, 2022). "Neither weight loss, depression, testosterone, androstenedione, DHEA, insulin, HOMA-IR nor cortisol did mediate this effect." (PMID 35581616, 2022). "Moreover, the effect of depression on HOMA-IR was partially mediated by PCSK9 level, providing a potential treatment strategy for the improvement of insulin sensitivity." (PMID 36387872, 2022). "For example, people with depression are more likely to smoke, and changes in body mass index (but not insulin levels) portend later depressive episodes, at least in young women." (PMID 35617679, 2022). "Depression is very common among people with DM, with reported rates as high as 17.8% compared with 9.8% in those without DM, and patients with depression are more likely to have concerns related to starting the treatment with insulin." (PMID 34062938, 2021). "The correlation between INS and DM has long been recognized worldwide, and AKT1, as a key factor in the PI3K-Akt signaling pathway, has been confirmed by many researches on its relationship with DM and depression, which will be discussed in detail below." (PMID 34875999, 2021). "Secondly, the lack of assessment of the insulin levels and depression in this study somewhat limited our conclusions." (PMID 34759889, 2021). "Insulin also increases BDNF mRNA levels and phosphorylation levels of Akt and GSK3b in a concentration‐dependent manner, thereby enhancing mouse memory in Y‐maze experiments and reducing depression‐like behaviour in forced swimming experiments." (PMID 32281722, 2020). "Among the other studies, some results were positive, and others negative for antidepressant effects of insulin and anti-hyperglycemic agents among subjects who were not diagnosed with depression." (PMID 32971941, 2020). "Collectively, there have been many investigations about the effects of insulin and blood glucose on depression, but the results are not identical." (PMID 32281722, 2020). "Collectively, results suggest that brain insulin signaling dysfunction could impair the HPA axis normal response to stress, possibly facilitating the development of depression." (PMID 30837902, 2019). "This study is in no way enough to establish that depression is more common in non-insulin dependent individuals." (PMID 31131177, 2019). "Among the DMRs specific to depression throughout pregnancy we found 1 KEGG pathway (related to insulin secretion) but no enriched biological process GO terms (FDR < 0.05)." (PMID 30405117, 2018). "LD score regression analysis revealed genetic correlations with childhood obesity, fasting insulin, T2D, HDL, menarche timing, triglyceride levels, cardiovascular diseases and depression suggesting that there is shared genetic architecture and biology between these phenotypes and PCOS." (PMID 30566500, 2018). "Multiple regression analyses revealed that CM contributed to reduced insulin sensitivity and lower disposition index independent of depression and visceral fat mass." (PMID 28713332, 2017). "A previous study found no increase in anxiety and depression symptoms in women with GDM when treatment was intensified from diet alone to insulin therapy." (PMID 28938877, 2017).